KRAS (KRas proto-oncogene, GTPase)
Diseases named in the same sentence as KRAS in open-access papers (continued):
Sharing a sentence is not in itself a finding about the gene and the disease.
pancreatic cancer (continued). "Further delineation of the presence of KRAS mutations in different stages of pancreatic cancer has been performed." (PMID 31608239, 2019). "This strongly suggests that the informative value of detecting KRAS mutations in pancreatic juice DNA with the purpose of early pancreatic cancer detection or differential diagnostics is limited." (PMID 30611220, 2019). "For example, RAS mutations in pancreatic cancer are almost exclusively KRAS mutations (greater than 95%), NRAS mutations are the predominant RAS mutations in melanoma (94%), and HRAS mutations are the most common RAS mutations in bladder cancers (54%)." (PMID 31878223, 2019). "DCLK1 is strongly linked to KRAS-mutant cancer, as evidenced by its expression in tumor stem-like cells in multiple KRAS-mutant pancreatic cancer mouse models." (PMID 31467540, 2019). "KRAS mutations, as detected with ctDNA, have also been associated with poor survival in pancreatic cancer." (PMID 31608239, 2019). "KRAS is often altered in pancreatic carcinoma, colorectal tumors and lung malignancies and HRAS mutations are common in dermatological malignancies and head and neck cancers whereas NRAS alterations in melanomas and in hematopoietic malignancies." (PMID 31681616, 2019). "Only in 1994 did the detection of amplifiable KRAS mutated copies in the serum of patients suffering from pancreatic carcinoma prove the tumor origin of a fraction of total ccfDNA." (PMID 31694149, 2019). "In this work, the authors selectively amplified KRAS-mutated alleles in ccfDNA of pancreatic carcinoma patients by means of allele-specific polymerase chain reaction (PCR) and confirmed their results by Sanger sequencing." (PMID 31694149, 2019). "The definite relations between mutations in the KRas proto-oncogenes and the tumorigenesis of pancreatic cancer make KRas one of the more attractive drug targets." (PMID 29467941, 2018). "KRAS is a well-known driver gene for pancreatic cancer, and mutation of this gene occurs in about 90% of patients." (PMID 29764514, 2018). "In plasma, most genomic DNA was associated to EVs, and genetic profiling (of EVs) identified tumour-related mutations such as KRAS in pancreatic cancer patients." (PMID 31162490, 2018). "The results of these trials were likely impacted by the fact that most pancreatic cancer patients are KRAS mutated." (PMID 29382159, 2018). "In the Project Achilles panel, all pancreatic cancers harbor KRAS‐activating mutations, while ovarian cancers infrequently do." (PMID 30573688, 2018). "Most KRAS mutations in pancreatic cancer are located in codon 12, while mutations in codon 13 and 61 are much less common." (PMID 29946224, 2018). "Of all the potential theranostic biomarkers of pancreatic cancer, mutations in the KRas genes are characterized by their particular frequency, approximately nine of tenth." (PMID 29467941, 2018). "NIK is elevated in pancreatic cancer and associated with increased proliferation and up-regulation of RelB and p52 are associated with mutated KRAS pancreatic cancer with IKKα dependent gene expression being observed." (PMID 30347849, 2018). "Since early PanIN lesions harbor mutations or amplification of the KRAS at high frequency (over 90%), it has been proposed that KRAS mutation is responsible for PanIN formation and thus is an initial event during pancreatic cancer development." (PMID 29802314, 2018). "Since the presence of KRAS mutations is used as the standard for identifying ctDNA in patients with pancreatic cancer, we compared the ability of our method to detect KRAS mutations to that of conventional deep sequencing." (PMID 29451897, 2018).
pancreatic cancer (continued). "Pancreatic cancer constitutes a genetic disease in which somatic mutations in the KRAS proto-oncogene are detected in a majority of tumors." (PMID 30533257, 2018). "In the case of PAAD, where more than 94% Pancreatic cancer patients harboring KRAS mutations, there is also a strong association between KRAS mutation status and increased level of expression of NRAS." (PMID 30517129, 2018). "Our gene expression analysis based on pancreatic cancer cell lines also showed that different KRAS mutation subtypes had different gene expression profiling." (PMID 30419860, 2018). "The metabolism of pancreatic cancer is profoundly rewired by KRAS mutations, offering new opportunities for selective targeting." (PMID 31225458, 2018). "The oncogenic signaling driven by KRAS mutation is necessary to fuel pancreatic tumors by activating key metabolic processes, including enhanced glycolysis and glutamine consumption." (PMID 31225458, 2018). "A recent study utilized genetically modified extracellular vesicles to directly and specifically target KRAS mutations frequently associated with pancreatic cancer." (PMID 29850495, 2018). "Walensky and colleagues designed a molecule which blocked nucleotide association with KRas in vitro and decreased the viability of the mutant KRasG12D pancreatic cancer cells with an IC50 of ~10 μM." (PMID 29467941, 2018). "KRAS mutations are present with high frequency in pancreatic intraepithelial neoplasias (PanINs), precursor lesions to pancreatic cancer, suggesting an initiating role for mutant KRAS." (PMID 29367463, 2018). "Lung and gastrointestinal cancers commonly harbor KRAS mutations, with 90–95% of pancreatic cancer lesions (particularly pancreatic ductal adenocarcinoma (PDAC)) carrying a point mutation at the G12 locus, the most common being KRASG12D and KRASG12V." (PMID 30283732, 2018). "Illustrating this, BRAF V600E and NRAS Q61R appeared to be selected more strongly than KRAS G12D in melanoma and thyroid cancer, but more weakly than this mutation in pancreatic cancer." (PMID 29748584, 2018). "An anomaly in the field is the discrepancies between values often quoted for RAS mutations ranging from 15 to 30% of all cancers harbouring a RAS mutation and 60 to 98% of pancreatic cancers harbouring KRAS mutations." (PMID 30287508, 2018). "The EpCAM−, CK+, CD45− cells captured by rVAR2 were confirmed to be genuine CTCs by KRAS mutation analysis on single cells from pancreatic cancer patient blood samples." (PMID 30115931, 2018). "In pancreatic cancer cells, KRAS mutations induce increased levels of the TNF-receptor family member TRAF6, which has a role in maintaining cell survival." (PMID 29184971, 2018). "The KRAS proto-oncogene is mutated in 90% of pancreatic cancers, leading to a constitutively active pathway resulting in rapid proliferation and increased survival." (PMID 30459936, 2018). "The PI3K/PTEN/Akt/mTORC1 is a key pathway activated in pancreatic cancer, likely due to its association with KRAS." (PMID 29382159, 2018). "Ninety percent of patients with pancreatic cancer have activating KRAS mutations, which attribute to the poor prognosis." (PMID 29184971, 2018).
pancreatic cancer (continued). "KRAS is mutated in more than 90% of pancreatic cancer and is a central driver of pancreatic tumor growth and progression." (PMID 29946224, 2018). "The differential sensitivity of pancreatic cancer cells to MEK inhibition can be attributed to the KRAS mutational subtype, copy number and the presence of PIK3CA co-mutation." (PMID 29435178, 2018). "Mutated KRAS is a major driver for malignant transformation in pancreatic tumors and in lung adenocarcinoma, as G12C mutations are detected in early lesions, retained in all metastases and are a hallmark in the exposure to tobacco smoke, respectively." (PMID 29534749, 2018). "More specifically, in pancreatic cancer, KRAS mutations result in a constitutively active protein which upregulates the PI3K/Akt cascade; the suppression of which is not feasible due to loss of PTEN in earlier stages of the disease." (PMID 29064423, 2017). "More than 90% of pancreatic cancer patients show KRAS mutations, including a low grade of pancreatic intraepithelial neoplasm, a pancreatic cancer precursor." (PMID 28435405, 2017). "The mutation of KRAS in pancreatic cancer induces long-term activation of the P21 RAS protein, which is a small guanosine triphosphatase (GTPase)." (PMID 28103577, 2017). "Till now, large numbers of miRNAs are implicated in the pathogenesis and progression of pancreatic cancer, including KRAS-related miRNAs (e. g. miR-217), TGF-β-related miRNAs (e. g. miR-483), miR-155, miR-21, miR-34 and so on." (PMID 28369140, 2017). "Despite the near universal occurrence of activating codon 12 KRAS somatic variants in pancreatic cancer, there is considerable heterogeneity in the molecular make-up, MAPK/ERK pathway activation states, and clinical outcome in this disease." (PMID 28732488, 2017). "We further examined the mutation status of KRAS and its three candidate synthetic lethal partners in published colorectal and pancreatic cancer cell lines." (PMID 28415695, 2017). "KRAS is of particular importance as the activating point mutation in the KRAS oncogene found in 90% of pancreatic cancer cases and it comprises one of the initial genetic mutations in non-cancerous precursor lesions." (PMID 28587243, 2017). "A feature of pancreatic cancer, and one of its earliest molecular changes, is a constitutively activating oncogenic KRAS mutation." (PMID 28163917, 2017). "KRAS mutations are found in a variety of human cancers, including pancreatic cancer, non-small cell lung cancer, and CRC." (PMID 28749408, 2017). "The KRAS mutation is very common in pancreatic cancer, occurring in approximately 90% of all patients, and it can lead to tumor development and drug resistance." (PMID 28797284, 2017). "To improve the sensitivity of pancreatic cancer diagnosis and to avoid additional punctures, we have applied the KRAS mutation analysis technique with modified PCR technology using the washing fluid after EUS-FNA." (PMID 27974679, 2017).
pancreatic cancer (continued). "A meta-analysis had clarified that KRAS mutations in cfDNA had a more significant impact on overall survival of patients with pancreatic cancer compared with KRAS mutation detected in tumor tissue." (PMID 28796802, 2017). "5, High frequency of downstream KRAS mutations in patients with pancreatic cancer was also considered as a potential explanation." (PMID 28427155, 2017). "Since activating mutations of KRAS are found in over 90% of pancreatic cancers, we conjectured that oncogenic KRAS signaling would primarily regulate ARHGEF2 expression in PDAC cells." (PMID 27835861, 2017). "A meta-analysis of pancreatic cancer patients showed a significant association between KRAS gene mutations and overall survival." (PMID 28103577, 2017). "These investigators noted that the mutant allele fraction was significantly lower (0.2% to 1%) when compared to the mutant KRAS allele fraction in patients with pancreatic cancer (1% to 50%)." (PMID 28199989, 2017). "Our meta-analysis showed that KRAS mutation detected in cfDNA was a significant prognostic biomarker of cancer patients, especially in pancreatic cancer." (PMID 28796802, 2017). "Previous studies have demonstrated that oncogenic GTPase KRAS mutation is involved in the initiation of pancreatic intraepithelial neoplasia and activates the progression of pancreatic cancer, especially pancreatic ductal adenocarcinoma." (PMID 28103577, 2017). "The glucose transporter GLUT1 is highly expressed in glycolytic tumors, such as KRAS mutated pancreatic cancers, yet our SILAC experiments show that it is further upregulated upon CD147 knockdown." (PMID 28039486, 2017). "Multiple studies using digital PCR have demonstrated that high levels of circulating KRAS mutations in pancreatic cancer patients adversely affect survival." (PMID 29137355, 2017). "Pancreatic cancers developed in KRAS-induced carcinomas and NUPR1-deficient mice exhibited a higher expression of stemness markers (ALDH1, SOX2, Oct-4) compared to tumors originated in NUPR1-WT mice." (PMID 29156578, 2017). "With respect to pancreatic cancer, it is known that pancreatic tumor growth relies on autophagy, especially in KRAS mutated cells where metabolism is deprogrammed." (PMID 28415695, 2017). "Three patients with pancreatic cancer that harbored a KRAS mutation in codon 12 (G12D) also achieved a best response of stable disease." (PMID 27853997, 2017). "For KRAS mutant driven tumors, non-small cell lung cancers tend to carry G12C mutations, while the G12D substitution is predominantly found in pancreatic cancer." (PMID 28815022, 2017). "Whereas inhibition of the MAPK pathway by the MEK1/2 inhibitor U0126 decreases Gli1 stability and suppresses the Gli1-mediated transcriptional activity in a KRAS-mutated pancreatic cancer cell line." (PMID 29163356, 2017). "In vitro, AGR2 expression was stimulated by tunicamycin-induced endoplasmic reticulum (ER) stress in both KRAS wild-type normal pancreas cells, as well as in KRAS mutated pancreatic cancer cells and was essential for ER homoeostasis." (PMID 27941872, 2017). "Ninety-five percent of pancreatic cancers carry activating mutations in KRAS and modifications in G12 account for 99% of all mutations (G12D—50%)." (PMID 28452926, 2017).
pancreatic cancer (continued). "A near universal feature of pancreatic cancer, and one of its earliest molecular changes, is a constitutively activating oncogenic KRAS mutation." (PMID 28163917, 2017). "If we only take KRAS mutations into consideration MiaPaCa2 (1.5%), Panc1 (31.2%) and BxPC3 (23%) represent more than the half of investigated pancreatic cancers." (PMID 28957417, 2017). "Here we demonstrate that DNA2 is overexpressed in pancreatic cancers, one of the deadliest and more aggressive forms of human cancers, where mutations in the KRAS are present in 90–95% of cases." (PMID 28414320, 2017). "The CXCR2 is induced by mutated KRAS in pancreatic cancer cells and is required for autocrine growth of tumor cells and for inhibition of oncogene-induced senescence." (PMID 29156578, 2017). "KRAS is mutated in approximately 90% of pancreatic cancer cases but all efforts for its direct targeting have proven unfruitful." (PMID 29064423, 2017). "Of importance, KRAS is mutated in more than 90% of pancreatic cancers and 35% of lung adenocarcinomas." (PMID 29018205, 2017). "Why KRAS mutations prevail in colorectal, lung and pancreatic cancer, while NRAS or BRAF are mutated more frequently in skin melanoma, and HRAS mutations are predominant in head and neck squamous cell carcinoma is not yet clear." (PMID 28152508, 2017). "In Korean pancreatic cancer patients, 54% KRAS mutations were reported to commonly occur as G12D (GGT → GAT, 31%) and G12 V (GGT → GTT, 34%) on codon 12 by Sanger sequencing." (PMID 28435405, 2017). "To assess the functional involvement of EVI1-GPC1 axis in PDAC carcinogenesis, we performed whole expression analysis in pancreatic cancer cell models (KRAS-mutated PK-45H cell lines) with siGPC1 or siEVI1 using gene expression microarray analysis." (PMID 29245923, 2017). "Consistent with the genetic pathology of pancreatic cancer, all patient samples also had somatic KRAS mutations." (PMID 28163917, 2017). "KRAS mutations are extremely common in cancer of the pancreas, colon, and lung, while NRAS mutations predominate in melanoma and hematopoietic cancers." (PMID 28378457, 2017). "Not only are activating Ras mutations the most common oncogenic alteration among solid cancers, it is well established that mutations that constitutively activate KRas are an early event in the pathogenesis of nearly all pancreatic cancers." (PMID 27602776, 2017). "This range of KRAS mutation detection is mainly due to the following factors: different stages of pancreatic cancer examined (i.e. late stage unresectable 81% vs earlier stage primary operable 27%) and differences in methods and sensitivity of these methods." (PMID 29152076, 2017). "In pancreatic cancer, a recent report showed that Ras/Raf/MEK/ERK activation induced by KRAS mutations, which are frequently observed in pancreatic cancer, plays important roles in reducing FBXW7 expression." (PMID 29348852, 2017). "A previous meta-analysis had suggested that KRAS mutation was associated with a poorer overall survival in patients with pancreatic cancer, especially when the mutation detection was performed by the circulating tumor DNA." (PMID 28796802, 2017). "The combination of cytological analysis with KRAS mutation status improves diagnostic accuracy for cytological diagnosis of pancreatic cancers by endoscopic ultrasound-guided fine-needle aspiration biopsy (EUS-FNAB)." (PMID 26999437, 2016). "Similar proportions of KRAS mutations at codons 61 and 13 were observed in cfDNA of pancreatic cancer cases (7.2% and 3.1% respectively) as compared to PDAC ICGC tumors (6.1% and 1.7% respectively)." (PMID 27705932, 2016).